STAT3 (signal transducer and activator of transcription 3)
Diseases named in the same sentence as STAT3 in open-access papers (continued):
Sharing a sentence is not in itself a finding about the gene and the disease.
tumor (continued). "Cucurbitacins can effectively inhibit STAT3 phosphorylation, thereby limiting its transcriptional activity and thus suppressing tumor growth." (PMID 37887406, 2023). "The accumulation of ETBF strains in crypts has been shown to be essential for tumor formation via activator of transcription 3 (STAT-3) and an IL-17-dependent pro-carcinogenic inflammatory response." (PMID 37265504, 2023). "As an important signal transducer and activator of transcription in cells, STAT3 is abnormally activated in a variety of cancers and promotes the progression of tumor cells and is also an important therapeutic target." (PMID 37076047, 2023). "In one study, exogenous histidine administration resulted in a decrease in the expression of tumor markers associated with glycolysis (GLUT1 and HK2), inflammation (STAT3), angiogenesis (VEGFB and VEGFC), and stem cells (CD133)." (PMID 37760495, 2023). "Nonetheless, in this study another anti-tumor molecular mechanism of TMZ was revealed: preventing cell growth by inhibiting STAT3 signaling." (PMID 37298405, 2023). "A decrease in IL-6 promotes macrophage polarization and subsequently lowers STAT3 activity, thereby reducing tumor development in cancer-prone mice fed with inositol diet." (PMID 37194070, 2023). "This has led to the preclinical and clinical development of various IL-6/STAT3 inhibitors targeting the IL-6/JAK/STAT3 components in order to inhibit tumor growth and reduce immunosuppression in the tumor microenvironment." (PMID 37762522, 2023). "W2014-S, a novel STAT3 inhibitor, can significantly enhance the anti-tumor effect of EGFR-TKIs in TKI-resistant NSCLC." (PMID 37649478, 2023). "The results of the current study revealed that STK24-mediated tumor angiogenesis was dependent on STAT3/VEGFA signaling pathway." (PMID 36720310, 2023). "The role of STAT3 in tumor formation and progression has been extensively studied in many human cancers, including HNSCC." (PMID 36446524, 2023). "In tumor models of colon and pancreatic cancers, TAMs produce IL-6 by activating the STAT3 signaling pathway to promote the proliferation of colon tumor cells." (PMID 36739406, 2023). "In conjunction with this evidence, EGFR-mediated constitutive activation of STAT3 leads to tumor advancement and apoptotic dysregulation in squamous cell carcinoma." (PMID 38170015, 2023). "Overexpression of STAT3 promotes the growth and development of tumor cells by regulating the IME, which is significantly related to poor prognosis in cancer patients." (PMID 37724127, 2023). "Activation of the IL-6/JAK2/STAT3 signaling pathway is involved in the development and progression of tumors and contributes to the formation of the tumor inflammatory microenvironment." (PMID 37817809, 2023). "Next, the effect of vortioxetine hydrobromide on the protein levels of Ki67 and p-STAT3 Y705 in tumor tissues were determined by immunohistochemistry (IHC)." (PMID 37147297, 2023). "Studies in other cancer types suggest that STAT3 inhibition impedes the local proliferation of TAMs, thereby reducing their abundance within the tumor." (PMID 38087370, 2023). "By acting as both serine/threonine protein kinase and tyrosine protein kinase, PKM2 binds to and phosphorylates multiple transcription factors such as β-catenin and STAT3 in the nucleus to promote tumor-related gene transcription." (PMID 37196116, 2023). "The Janus kinase/signal transducer and activator of the transcription 3 (JAK/STAT3) signaling pathway has an important role in tumor behavior and function." (PMID 37063281, 2023). "Overall, leptin is associated with a STAT3-mediated metabolic reprogramming of CD8+ T-cells, which compromises their anti-tumour properties." (PMID 37173907, 2023). "STAT3 overactivation in tumor-infiltrating immune cells impairs antitumor immunity by compromising native immune responses via multiple mechanisms, including polarized macrophages toward the M2 phenotype." (PMID 38001876, 2023).
tumor (continued). "Animal models have shown that TAMs activation in cancer cells leads to STAT3‐mediated Sox2 expression, resulting in an increase in the number of tumor stem cells and metastasis in a mouse breast cancer model." (PMID 38077251, 2023). "The accumulated body of evidence underscores the pivotal role of the IL-6/STAT3 signaling pathway in steering tumor metastasis and invasion." (PMID 37813837, 2023). "Taken together, WCP exerted its anti-tumor effects probably through the Cyto-c/Caspase8/3 and IL-10/STAT3/Bcl2 pathway in H22-tumor-bearing mice." (PMID 37110586, 2023). "JAK/STAT3 signaling pathway drives tumor cell proliferation, survival, invasion, and metastasis while suppresses anti-tumor immune responses (Johnson, O’Keefe & Grandis, 2018)." (PMID 37404473, 2023). "Along with the mutated genes for JAK in the occurrence of some tumors, IL-6 also contributes to JAK/STAT3 constitutive activation in tumor cells, thus enabling proliferation, survival, and suppression of antitumor immune response." (PMID 37176160, 2023). "These ingredients can potentially decrease the levels of inflammatory cytokines (such as IL-6 and TNF-α), inhibit the expression of tumor-related factors (such as JAK2/STAT3, MMP-9, and vimentin), and increase immune cell activity." (PMID 37742025, 2023). "IL-6/STAT3 signaling has an important consequence on tumor-infiltrating immune cells in the tumor immune microenvironment in CRC." (PMID 36835094, 2023). "Because of the role of the STAT3 signaling pathway in tumor formation and metastasis, most scholars regard it as a potential therapeutic target for cancer therapy." (PMID 36714534, 2023). "According to a prominent study team, blocking STAT3 reduces tumor development with little impact on healthy cells." (PMID 36852795, 2023). "STAT3 has a unique function in controlling the differentiation of MDSCs into TAMs in the tumor environment." (PMID 37547175, 2023). "FOXP3+ Tregs in the TME are a significant cause of tumor-induced immunosuppression and highly express CTLA4101, and the transcription factor STAT3 is necessary and sufficient for Treg development." (PMID 37653036, 2023). "Using phosphoflow cytometry, reduced IL-4, IL-10, and IL-21-induced p-STAT6 and p-STAT3 were identified in tumor infiltrating lymphocytes (TILs) in follicular lymphoma tumors." (PMID 37741983, 2023). "Nanostring GeoMx® digital spatial profiling was utilised to establish the differential spatial gene expression in high STAT3 tumours." (PMID 37199043, 2023). "Several oncogenic signaling pathways, including Src/STAT3, EGFR, HER2, MAPK, AKT/mTOR, WNT/-catenin and miRNA-related pathways, have been associated with changes in tumor cell surface CD24 expression." (PMID 37846296, 2023). "The tumor mitotic index (Ki67) and STAT3 signaling pathway in tumor tissues were further evaluated by immunohistochemistry (IHC)." (PMID 37240202, 2023). "STAT3 is a transcription factor that plays a crucial role in the growth and proliferation of cells, including tumor cells." (PMID 37946196, 2023). "Tumor formation after the injection of 4T1/STAT3-silenced cells was inhibited in mice compared with the injection of control cancer cells." (PMID 38067351, 2023). "The reason for this is a promotion of STAT3 activity both in tumor cells and populations of immune and CAF cells, followed by creation of an immunosuppressive environment." (PMID 37448521, 2023). "In carcinoma-associated fibroblasts (CAFs), which mediate the initiation of a pro-invasive tumor microenvironment, p300-histone acetyltransferase acetylates STAT3, which in turn upregulates and activates DNMT3b DNA methyltransferase." (PMID 38203502, 2023).
tumor (continued). "Tumor-induced STAT3 activation in MDSCs enhances stemness and mesenchymal properties in pancreatic cancer." (PMID 37534250, 2023). "6-Shogaol strongly inhibited the native phosphorylation of STAT3 by suppressing Jak2 and c-Src activity and nuclear translocation of STAT3 on tumor cells, thereby inhibiting STAT3 signaling." (PMID 37875983, 2023). "These collective findings underscored the potential of PRMT6 as a viable therapeutic target in the context of STAT3-driven tumor metastasis." (PMID 37813837, 2023). "OS‐associated macrophages (tumor‐associated macrophages) promote metastasis and EMT of OS cells by elevating the expression levels of p‐STAT3,116 MMP‐9, and COX‐2." (PMID 37441462, 2023). "show that the co-culture of MSCs with osteosarcoma cells leads to increased resistance to doxorubicin or cisplatin in tumor cells through a STAT3-dependent pathway." (PMID 38022534, 2023). "Acknowledging the pivotal role played by the IL-6/STAT3 signaling pathway in tumor progression, efforts to hinder its hyperactivity have involved the exploration of therapeutic strategies such as IL-6 receptor mono-antibodies or STAT3 inhibitors." (PMID 37813837, 2023). "In this study, we further found that miR-506 can also repolarize M2-like macrophages, acting as a tumor-suppressive regulatory molecule by targeting the STAT3 pathway." (PMID 38001876, 2023). "The IL-6/STAT3/Twist pathway is critically important in the development of cancer, and impacting tumour cell growth, proliferation, and migration." (PMID 37742025, 2023). "Heteronemin can effectively antagonize HGF/c-Met/STAT3 activation and tumor proliferation in refractory PCa cells." (PMID 36959792, 2023). "While all recipients (10/10) given TCD-BM alone died with progressive tumor growth by 20 days after HCT, addition of STAT3–/– T cells eliminated the BCL1/Luc+ tumor cells by 10 days after HCT, and most (6/10) of the recipients survived for more than 100 days." (PMID 37526084, 2023). "Accumulating evidence indicates that activation of the IL-17/JAK/STAT3 pathway plays a significant role in tumor metastasis and growth." (PMID 37894738, 2023). "DC-Me49-exo was also shown to exert an anti-tumor effect mainly by inhibiting the STAT3 signaling pathway to reduce the proportion of MDSCs." (PMID 37553810, 2023). "STAT3 plays a role in astrocyte development and has tumor suppressive roles in glial malignancies; this target shows promise in laboratory research using tetrandrine as an inhibitor." (PMID 37445633, 2023). "Future studies are needed to examine the potential interplay between STING signaling and HIF-1α or STAT3 in tumor-infiltrating DCs." (PMID 36821379, 2023). "Negative regulation of the IL-6/JAK2/STAT3 signaling pathway enhanced apoptosis and autophagy in tumor cells, thereby improving the therapeutic effect on GBM." (PMID 37057281, 2023). "Among them, IL-6 is one the most proinflammatory cytokines found in the TME, in both experimental and human colon cancer models, which has been associated with CRC progression and metastasis through activation of the STAT3 pathway axis in tumor cells." (PMID 37760840, 2023). "For the STAT3 signaling pathway, little work has focused on its involvement in nuciferine-suppressed tumor progression." (PMID 37833979, 2023). "In previous studies, Stat3 is thought to be a critical transcription factor regulating angiogenesis in a variety of diseases and tumours." (PMID 37309689, 2023). "Our data provide evidence that a subset of MB tumor-initiating cells have the ability to form tumor-spheres in serum-free conditions in vitro, which is dependent on STAT3 expression." (PMID 37190167, 2023). "VEGF is a critical pro-angiogenic factor highly expressed in tumour development through the over-activation of STAT3 that, in turn, activates gene expression mediated by HIF-1α." (PMID 37896150, 2023).
tumor (continued). "Natural furanocoumarins (bergamottin (BGM)) extracted from grapefruit juice induce apoptosis to destroy tumor cells through inhibition of the signal transducer and activator of the transcription 3 (STAT3) pathway." (PMID 36672732, 2023). "Aberrant expression of IL-6/STAT3 has also been shown to contribute to tumor aggressiveness and lower survival in CRC patients and AOM/DSS-induced CAC model mice 13-15." (PMID 37771783, 2023). "Two STAT3 PROTACs, SD-36 and SD-91, exhibit tumor-inhibitory effects in vivo and are safe in animals." (PMID 39872303, 2023). "A single 50 mg/kg dose of SD-36 reduced the levels of STAT3 and pSTAT3Y705 by > 95% in the mice tumor tissue of MOLM-16 xenografts." (PMID 36986673, 2023). "Overexpression of EZH2 accelerated STAT3 phosphorylation at pY705, leading to tumor glycolysis, invasion, migration, and epithelial-mesenchymal transition in OSCC." (PMID 37476905, 2023). "Compound 25 had little effect on p-JAK, p-STAT1, p-STAT5, or other signaling pathways, implying that compound 25 selectively reduced STAT3 activation in tumor cells." (PMID 37240202, 2023). "Signal transducer and activator of transcription 3 (STAT3) is one of the most critical signal molecules in tumor cells." (PMID 36961655, 2023). "SP at 20 mg/mL (2 w/v%) in drinking water suppressed tumor growth by downregulating STAT3 and activating p38 in JIMT-1 and MCF-7 xenograft mouse models." (PMID 37240357, 2023). "MDCS also enhanced tumor proliferation in both tumor cell lines, indicating that MDCS is correlated with tumor proliferation via STAT3 activation in SCLC cells." (PMID 36961655, 2023). "Other investigators have also asserted that aloin is effective in lowering tumor angiogenesis and growth by blocking STAT3 activation in CRC cells, which, in turn, controls the expression of the antiapoptotic protein Bcl-xL gene." (PMID 37894369, 2023). "In the adaptive immune subgroup, elevated STAT3 activity can inhibit the aggregation of effector T cells, thereby inhibiting their anti-tumor effects." (PMID 37799727, 2023). "Overall, these data suggested that tumor inhibition by STAT3 inhibitors was at least partially dependent on CD146 expression in macrophages." (PMID 37308559, 2023). "Second, HOTAIR down-regulates the expression of E-cadherin and miR-217, then activates the DACH1/JAK3/STAT3 and Wnt/β-catenin pathways, which are involved in the tumor’s EMT ability, which is important for primary tumor formation and metastasis." (PMID 36924407, 2023). "Meanwhile, a variety of immunosuppressive cells such as M2 tumor-related macrophages, myeloid inhibitory cells, and regulatory T cells were recruited by STAT3, thereby inhibiting the immune response." (PMID 36923251, 2023). "Blocking STAT3 activity in tumor cells induces DC maturation and activation and the consequent T cell activation." (PMID 39872303, 2023). "Depletion of RAP1A or STAT3 disrupted normal microtubule dynamics that sensitized tumor cells toward the microtubule-targeting agents." (PMID 37480054, 2023). "They found that the overexpression of STAT3 in these samples was associated with an increase in the expression of Bcl6, a protein that plays a crucial role in EMT, tumor progression, decreased survival, and the viability of BCSCs." (PMID 37958993, 2023). "Eckol, a novel natural phizolian derived from marine brown algae, has been shown to downregulate EGFR, p-EGFR, JAK2, and STAT3 expression in tumor cells, indicating pro-apoptotic and anti-proliferative activities." (PMID 37859983, 2023). "Ultimately, low cholesterol levels through combined fasting and CBIs reduce AKT and STAT3 activity, oxidative phosphorylation and energy stores in the tumour." (PMID 37907500, 2023). "Further, lactate-Gpr81 signaling has been reported to be regulated by the PPARγ in adipocytes and the snail 3/STAT3 pathways in tumor cells pathways." (PMID 37564659, 2023).
tumor (continued). "Gemcitabine (GEM) is a chemotherapeutic drug that inhibits MDSCs through the selective blockage of the JAK/STAT3 pathway, responsible for their formation, inhibiting the immunosuppressive effects in the tumor microenvironment." (PMID 36987269, 2023). "IL-6/STAT3 signaling promotes tumor cell proliferation, metastasis, angiogenesis, immune suppression, cancer stemness and chemotherapeutic resistance." (PMID 36614179, 2023). "When STAT3 is inhibited in tumor cells, the expression of Bcl-2, which is an anti-apoptotic gene, is reduced, and the apoptotic caspase 3 pathway is activated." (PMID 37369757, 2023). "Once activated within tumor cells, phosphorylated STAT3 (p-STAT3) regulates the transcription of various immunosuppressive cytokines such as VEGF, IL-10, and TGF-β." (PMID 36902166, 2023). "The constitutive activation of STAT3 plays a vital role in tumor formation, development, metastasis, and recurrence, and inhibition of STAT3 activation leads to tumor growth repression in several cancer cell lines." (PMID 37375411, 2023). "Mechanistically, TRIM29 functioned as a positive regulator of tumor suppressor gene ZNF750 via modulating IL6/STAT3 signaling pathway." (PMID 37365152, 2023). "Meanwhile, with the coordination of NF-κB and STAT3, TAMs often prime their cancer-fighting phenotypes toward a cooperative tumor development profile." (PMID 36978108, 2023). "As STAT3 activation promotes tumorigenesis through its effects on cell proliferation, differentiation, and anti-apoptosis, the STAT3 signaling pathway is a potential target for tumor therapy." (PMID 37057285, 2023). "STATs can be phosphorylated by different non-receptor tyrosine kinases; for example, the tyrosine kinase c-Src phosphorylates STAT3, which increases tumor-related gene expression." (PMID 37372319, 2023). "In conclusion, our results suggest that acetyl-cinobufagin, which suppresses EMT in BC by focusing on the STAT3 signaling pathway, is a possible candidate for tumor therapy." (PMID 37651362, 2023). "Recent studies reported that the IL-6/STAT3 signaling acted to drive proliferation, invasiveness, and metastasis of cancer cells, while strongly inhibited anti-tumor immunity." (PMID 37069669, 2023). "By detecting the expression of key proteins related to signalling pathways in tumor tissue, we found that the expression levels of p-Akt1 and p-STAT3 in the HDW groups were significantly lower than those of the model group." (PMID 36647454, 2023). "Multiplexed IF staining showed that CXCL6+ tumor cells were located near the SAAs+ hepatocytes in the invasive zone, which highly expressed STAT3 and C-X-C Motif Chemokine Receptor 2 (CXCR2), the receptor of CXCL635." (PMID 37337030, 2023). "The accumulation and differentiation of SDC1/CD138+ IgG-producing PCs can be modulated by tumor-associated neutrophils and myeloid-derived suppressor cells in a BAFF- or STAT3-dependent manner." (PMID 37138324, 2023). "It has been observed that the positive feedback autocrine loop between osteopontin and the JAK/STAT3 pathway results in the EMT process, which participates in the persistent enhancement of CSC-associated tumor metastasis." (PMID 37853437, 2023). "Aberrant activation of STAT3, observed in many human cancers, triggers tumor progression by upregulating oncogenic gene expression, thereby promoting tumor aggressiveness." (PMID 37511611, 2023). "In recent years, there has been an abundance of research demonstrating that blocking constitutive STAT3 signaling substantially inhibits tumor development and triggers apoptosis." (PMID 37894369, 2023). "What’s more, STAT3 was revealed to antagonize the sensitivity of tumor cells to Palbociclib (cor = −0.406, p = 0.001), LDK-378 (cor = −0.393, p = 0.002), and Tamoxifen (cor = −0.369, p = 0.004)." (PMID 36968603, 2023). "STAT3 signaling bears significant impact on the microglia transformation from the proinflammatory/antitumor M1 phenotype to the anti-inflammatory/tumor-promoting M2 phenotype." (PMID 38104104, 2023).